FUS (FUS RNA binding protein)
Diseases named in the same sentence as FUS in open-access papers (continued):
Sharing a sentence is not in itself a finding about the gene and the disease.
prostate carcinoma (23 papers, 2011 to 2026). A carcinoma that arises from epithelial cells of the prostate gland. "Particularly, gain- and loss-of-function approaches demonstrate that FUS inhibited prostate cancer cell growth in vitro and FUS overexpression in tumor xenografts led to strong tumor regression." (PMID 34299185, 2021). "Together these data support that AR and FUS associate within the same complex in prostate cancer cells." (PMID 21909421, 2011). "This co-localization is retained in carboplatin treated LNCaP cells, while occasional co-localization of FUS and Coilin is detected upon other platinum drug treatments in the prostate cancer cell lines tested." (PMID 38218884, 2024). "We also find that CB-associated, stress-responsive RNA binding proteins FUS and TDP-43 control Coilin and CB biology in prostate cancer cells and, further, that TDP-43 is associated with stress-responsive CBs in prostate cancer cells." (PMID 38218884, 2024). "Co-immunostaining with Coilin revealed that FUS is nucleoplasmic and exhibits clear localization in CBs only in LNCaP cells of the prostate cancer cell lines tested." (PMID 38218884, 2024). "These RBPs include e.g. FUS which interacts with AR,34, 35, 36 a key transcription factor driving prostate cancer." (PMID 37591798, 2023). "In prostate cancer, increased expression of FUS promotes cell death through activation of apoptotic pathways." (PMID 36263181, 2022). "Through western blotting, we found that there was negative correlation between the expression of ACAT1 and that of FUS in four common prostate cancer cell lines (LNCaP, PC3, DU145, and 22RV1) (R = -0.9148)." (PMID 36517760, 2022). "Here, we demonstrate that FUS harbors strong transactivation domains that were functional in prostate cancer cells." (PMID 21909421, 2011). "Overall, while further studies are needed to resolve the role of FUS in prostate cancer disease progression, this study revealed that: 1) FUS interacts with AR; and 2) FUS enhances the transcriptional activity of AR." (PMID 21909421, 2011). "In prostate cancer, circ0005276 interacts with FUS so as to initiate the transcription of XIAP." (PMID 36747292, 2023). "EMX2OS is a key metabolism-related enhancer RNA in KIRC with a favorable impact on survival and EMX2OS is regulated by TCF12 transcription and co-regulates the proliferation, migration and invasion of prostate cancer cells with FUS protein by activating cGMP-PKG pathway." (PMID 33517850, 2021). "A previous study has revealed that HDAC6 interacted with FUS in prostate cancer cells." (PMID 34307380, 2021). "Here, we employed the GAL4 transactivation assay to explore if transactivation activity could be attributed to FUS in prostate cancer cells." (PMID 21909421, 2011). "Expression of FUS is responsive to hormone status in prostate cancer cells." (PMID 21909421, 2011). "Thus, there are functional transactivation domains in FUS other than those found in its NTD at least in prostate cancer and 293 cells." (PMID 21909421, 2011). "Therefore, in prostate cancer, FUS is regarded as a tumor suppressor." (PMID 36517760, 2022). "Thus, FUS is a novel co-activator of AR in prostate cancer cells." (PMID 21909421, 2011). "We first tested by immunostaining how FUS and TDP-43 respond to platinum-based drugs in prostate cancer cells." (PMID 38218884, 2024). "In prostate cancer, ACAT1 inhibited autophagy or oxidative stress by preventing FUS from transcribing LC3B or scavenging ROS, thereby promoting tumorigenesis." (PMID 38817856, 2024). "Hence, we then tested for functional significance of FUS and TDP-43 for CBs in prostate cancer cells." (PMID 38218884, 2024). "Besides, circ0005276 was found to recruit FUS to increase mRNA stability of XIAP, thereby promoting prostate cancer progression." (PMID 38012555, 2023). "which implied that RBP FUS and UPF1 with lncRNA RP11-423H2.3 or LAMTOR5-AS1 interactions might affect prostate cancer progression." (PMID 32117463, 2020).
prostate carcinoma (continued). "Analysis of levels of FUS mRNA in various prostate and non-prostate cancer cell lines did not reveal systematic differences." (PMID 21909421, 2011). "Having demonstrated a transactivation capacity of FUS that was independent of the promoter in prostate cancer cells we next evaluated the involvement of FUS specifically in AR transcriptional activity at target genes." (PMID 21909421, 2011). "Through laser confocal microscopy, we observed that FUS could co-localize with ACAT1 in the cytoplasm in prostate cancer cells, and FUS not bound to ACAT1 existed in the nucleus of some prostate cancer cells." (PMID 36517760, 2022).
breast cancer (21 papers, 2008 to 2026). A primary or metastatic malignant neoplasm involving the breast. "Aberrant splicing mediated by FUS is a crucial mechanism underlying neurodegenerative diseases, and dysregulated FUS also contributes to breast cancer progression 40,41." (PMID 41510173, 2026). "CircROBO1 promotes the development and liver metastasis of breast cancer through the circROBO1/KLF5/FUS feedback loop." (PMID 41229443, 2025). "In breast cancer, FUS binds to circAAGAB under hypoxic conditions, increasing the stability of circAAGAB and enhancing the radiation sensitivity of breast cancer cells through the p38/MAPK pathway." (PMID 40290118, 2025). "In CDK4/6 inhibitor-resistant ER+/RB-deficient breast cancer, PRMT5 inhibition represents a viable therapeutic strategy, leading to the dissociation of FUS from RNA polymerase II and subsequently suppressing the DNA synthesis." (PMID 39678513, 2024). "Analysis of the data from Metabric and The Cancer Genome Atlas (TCGA) databases revealed that FUS expression levels were significantly higher in breast cancer tissues than in normal tissues, suggesting its potential as an oncogene in breast cancer." (PMID 36806670, 2023). "By enhancing the epithelial-mesenchymal transition, the FUS/circEZH2/KLF5 feedback loop promotes CXCR4-induced liver metastasis of breast cancer." (PMID 37670963, 2023). "The PGC gene FUS1 (also known as FUS) has been reported as a tumor suppressor gene in lung and breast cancer and a pro-oncogene in leukemia." (PMID 18636107, 2008). "This circROBO1/KLF5/FUS positive feedback loop accelerates liver metastasis in breast cancer." (PMID 40290118, 2025). "Meanwhile, lncRNA DLX6-AS1 enhances invasion and migration by upregulating FUS and breast cancer." (PMID 35599603, 2022). "In our experiments with MCF7 breast cancer cell line we found FUS and other paraspeckle proteins localized predominantly in the perinucleolar region in the vast majority of cells, a pattern strikingly different to distribution of these proteins in the nucleus of other types of cultured cells." (PMID 24334610, 2014). "Additionally, NEAT1 physically interacts with FUS, promoting cell growth in breast cancer." (PMID 39715205, 2024). "However, the molecular transport and interaction between FUS and circRNAs in breast cancer remain unclear." (PMID 36806670, 2023). "Furthermore, the silencing of FUS was found to promote the apoptosis of breast cancer cells." (PMID 32892482, 2020).
familial amyotrophic lateral sclerosis (21 papers, 2013 to 2026). An instance of amyotrophic lateral sclerosis that is caused by an inherited modification of the individual's genome. "For example, familial amyotrophic lateral sclerosis and frontal temporal lobar degeneration have been linked to mutations in the FUS gene which lead to increased DNA damage in neurons." (PMID 27425845, 2016). "FUS mutations can occur in familial amyotrophic lateral sclerosis (fALS), a neurodegenerative disease with cytoplasmic FUS inclusion bodies in motor neurons." (PMID 24912067, 2014).
glioma (21 papers, 2019 to 2025). A benign or malignant brain and spinal cord tumor that arises from glial cells (astrocytes, oligodendrocytes, ependymal cells). "In summary, our findings demonstrated that IL-13Rα2 expression was significantly associated with cytoplasmic distribution of FUS in human glioma samples." (PMID 37158824, 2023). "For instance, LINC00470 binds to fused in sarcoma (FUS) protein in glioma cells and sequesters FUS in the cytoplasm to enhance AKT activity and inhibit the ubiquitination of HK1, consequently regulating glycolysis and suppressing autophagy." (PMID 39272133, 2024). "To assess the protein expression and status of IL-13Rα2 and FUS in clinical glioma samples, we performed immunostaining with anti-IL-13Rα2 and anti-FUS." (PMID 37158824, 2023). "Pearson’s correlation analysis revealed a positive correlation between IL-13Rα2 and cytoplasmic FUS expression (p = 0.0129; r = 0.3565) in glioma." (PMID 37158824, 2023). "For instance, RBP FUS can regulate glioma angiogenesis through the FUS/circ_002136/Mir-138-5p/SOX13 feedback loop." (PMID 37322431, 2023). "For example, upregulated fused in sarcoma (FUS) and downregulated miR-138-5p were correlated with the regulation of angiogenesis with the mediator circ_002136 in glioma cells." (PMID 37426488, 2023). "We demonstrated that the interaction between BACH2 and FUS promoted glioma progression via transcriptional inhibition of TSLNC8." (PMID 32892482, 2020). "RBP FUS has been discovered to act as a tumor enhancer in several cancers such as thyroid cancer, non-small cell lung cancer and glioma." (PMID 32484203, 2020). "Interaction of BTB and CNC homolog 2 (BACH2) with fused in sarcoma (FUS) promoted glioma progression via transcriptional inhibition of TSLNC8." (PMID 32892482, 2020). "In this study, the dual knockdown of BACH2 and FUS was found to exhibit stronger inhibition of the malignant behaviour of glioma cells, indicating that the interaction enhanced the cancer‐promoting effect." (PMID 32892482, 2020). "Specifically, FUS binds to circ_002136 through RNA-IP and RNA pull-down assays, and inhibition of FUS or circ_002136 dramatically suppressed tube formation of U87 glioma-exposed endothelial cells (GECs)." (PMID 32061256, 2020). "Compared with NBTs, the expression of BACH2 and FUS was significantly increased in glioma tissues and with increasing pathological grade." (PMID 32892482, 2020). "The protein expression of BACH2 and FUS in different grades of glioma tissues and HA cells and U87 and U251 glioma cells was detected by western blotting." (PMID 32892482, 2020). "SOX13 bound to the FUS promoter region to up-regulate the expression of FUS, forming a positive feedback loop that promoted glioma angiogenesis." (PMID 30736838, 2019). "Other studies confirmed that RNA-binding proteins MOV10 and FUS also bound to circRNAs and positively regulated their expressions to promote the angiogenesis of gliomas, which is consistent with our results." (PMID 31296839, 2019). "Our data suggests that the feedback loop of FUS/circ_002136/miR-138-5p/SOX13 played a crucial role in the regulation of angiogenesis in glioma." (PMID 30736838, 2019). "Recently, FUS have reported to be upregulated in glioma tissues and cells, while downregulation of FUS significantly inhibits the malignant behavior of glioma cells, which suggests that FUS may act as an oncogene." (PMID 37158824, 2023). "In conclusion, we report that HOTAIRM1 is conducive to maintaining the malignant phenotype of tMSCs transformed by GSCs in the glioma microenvironment via E2F7 by binding to FUS and that the HOTAIRM1/FUS/E2F7 axis may be a potential target for glioma therapy." (PMID 35586206, 2022). "For instance, an RBP FUS was found to bind to circ_002136 and govern the angiogenesis in glioma." (PMID 34774079, 2021). "SOX13 promoted FUS transcription to form a feedback loop that regulated glioma angiogenesis." (PMID 34116651, 2021).
glioma (continued). "We found that FUS was upregulated in glioma tissues and cells." (PMID 32892482, 2020). "We studied the interaction between BACH2 and FUS and its contribution to glioma progression." (PMID 32892482, 2020). "Moreover, compared with HA cells, a significant upregulation of BACH2 and FUS protein expression was found in both U87 and U251 glioma cells." (PMID 32892482, 2020). "An immunofluorescence assay was used to detect the localisation of BACH2 and FUS in glioma cells." (PMID 32892482, 2020). "The downregulation of FUS significantly inhibited the malignant behaviour of glioma cells, suggesting that FUS may act as an oncogene." (PMID 32892482, 2020). "BACH2 and FUS/TSLNC8/miR‐10b‐5p/WWC3 axis is responsible for glioma development and could serve as a potential target for glioma therapies." (PMID 32892482, 2020). "IL-13Rα2 expression was significantly associated with cytoplasmic distribution of FUS in human glioma samples and could be the independent prognostic factors for OS, while the prognostic value of its co-expression with cytoplasmic FUS in glioma need to be addressed in the future studies." (PMID 37158824, 2023). "It is also well known that FUS can enter the nucleus and that mutation are associated with its cytoplasmic localization, which is associated with a variety of neurodegenerative diseases and suggests that cytoplasmic FUS might be a reliable indicator of glioma malignancy." (PMID 37158824, 2023). "However, in HGG, co-expression of IL-13Rα2 and nuclear and cytoplasmic FUS was correlated with worse OS, which suggested that the combination of these two markers might be a more precise approach to predict glioma progression." (PMID 37158824, 2023). "Interestingly, the interaction between BACH2 and FUS may represent a novel target for the treatment of glioma." (PMID 32892482, 2020). "In glioma, studies have indicated that FUS can interact with BACH2 (BTB domain and CNC homologue 2), thus promoting glioma progression." (PMID 35586206, 2022). "Circ_002136 can bind to a RBP, FUS, and this regulates angiogenesis via the miR-138-5p/SOX13 axis in glioma." (PMID 32894165, 2020). "This demonstrated that the interaction between BACH2 and FUS enhanced the negative regulation of TSLNC8 by BACH2, thus facilitating the viability, migration and invasion of glioma cells and the inhibition of glioma cell apoptosis." (PMID 32892482, 2020). "The present study investigated the expression of endogenous BACH2, FUS, TSLNC8 and miR‐10b‐5p in glioma tissues and cells." (PMID 32892482, 2020). "Here, we investigated the endogenous expression of BTB and CNC homolog 2 (BACH2), fused in sarcoma (FUS), TSLNC8 and microRNA (miR)‐10b‐5p in glioma cells and tissues." (PMID 32892482, 2020). "Collectively, this study revealed that the HOTAIRM1/FUS/E2F7 axis is involved in the maintenance of the malignant phenotype of tMSCs and may function as a novel target for glioma therapy." (PMID 35586206, 2022). "Moreover, the upregulated RNA‐binding protein in GECs, FUS, participated in the feedback loop of FUS/circ_002136/miR‐138‐5p/SOX13 and regulated the angiogenesis in glioma." (PMID 34482648, 2021). "Our results indicate that the BACH2 and FUS/TSLNC8/miR‐10b‐5p/WWC3 axis is responsible for glioma development and could serve as a potential target for the development of new glioma therapies." (PMID 32892482, 2020). "More importantly, SOX13 could enhance FUS transcription via promoter region, uncovering angiogenesis regulation mediated by the feedback loop of FUS/circ_002136/miR-138-5p/SOX13 in glioma." (PMID 32061256, 2020). "Our study revealed that the HOTAIRM1/FUS/E2F7 axis is involved in the malignant progression of tMSCs transformed by GSCs in the glioma microenvironment and may function as a novel target for glioma therapy." (PMID 35586206, 2022).
glioma (continued). "Taken together, these results indicate that BACH2 and FUS interaction enhanced the inhibition of the protein levels of WWC3 and YAP phosphorylation, TSLNC8 promoted the protein levels of WWC3 and YAP phosphorylation via miR‐10b‐5p and affected the malignant biological behaviour of glioma cells." (PMID 32892482, 2020).
leukemia (15 papers, 2008 to 2025). A malignant (clonal) hematologic disorder, involving hematopoietic stem cells and characterized by the presence of primitive or atypical myeloid or lymphoid cells in the bone marrow and the blood. "The FUS-ERG transcript found here was of type 5 which has hitherto only been reported in two other cases of childhood leukemia (in a 1-year-old boy and an 8-month-old boy) both diagnosed with precursor B cell ALL." (PMID 24068373, 2013). "The FUS-ERG transcript found here has been reported in only two other cases of childhood leukemia, in a 1-year-old boy and an 8-month-old boy, both diagnosed with precursor B cell ALL." (PMID 24068373, 2013). "However, whether it can be used for other leukaemias remains unknown because the analysis only included AML with FUS-ERG." (PMID 37660196, 2023). "To further explore the clinical significance of these hub genes (SUGP1, DHX16, FUS, HNRNPR, DHX15, NAA38, SKIV2L2, and PLRG1), we used a series of online tools to evaluate the clinical expression of these hub genes in leukemia." (PMID 31766457, 2019).
tauopathies (15 papers, 2016 to 2025). "FUS and TARDBP are FTLD genes, and DDX3X and TIA1 have been implicated in tauopathies." (PMID 37730840, 2023). "The underlying mechanism of bvFTD is the accumulation and deposition of abnormal pathological proteins, especially in the frontal–temporal brain regions, including tauopathy (TAU), TAR DNA-binding protein of 43 kDa (TDP-43), and fused-in-sarcoma (FUS)." (PMID 36890594, 2023). "Further pathological investigation is needed to clarify the role of FUS/SFPQ in the pathogenesis of FTLD/ALS and tauopathies." (PMID 30050404, 2018). "However, future pathological studies examining the FUS/SFPQ nuclear interaction in both FTLD/ALS and tauopathies are necessary." (PMID 29774215, 2018). "Accumulating in vitro and in vivo evidences indicate that FUS dysfunction might be involved in the pathomechanism of FTLD/ALS and other neurodegenerative diseases including tauopathies." (PMID 29774215, 2018). "In particular, the infTub region was affected only in the tauopathies, but not in the TDP-43 nor FUS groups." (PMID 35717886, 2022).
spinal muscular atrophy (14 papers, 2010 to 2024). A motor neuron disease that affect the muscles, and characterized by muscle weakness and atrophy resulting from progressive degeneration and irreversible loss of the anterior horn cells in the spinal cord (i.e., lower motor neurons) and the brain stem nuclei. "SMN protein, a known interactor of FUS, has been linked to spinal muscular atrophy (SMA) pathogenesis, and loss of SMN protein leads to RNA splicing defects as well as axonal and synaptic defects in cellular and animal models." (PMID 31811140, 2019). "Numerous RG/RGG-containing proteins have been implicated in neurological disorders, such as FUS and TAF-15 in ALS, FXR1, and FMRP1 in fragile X syndrome (FSX), SMN in spinal muscular atrophy (SMA), SHANK1 in autism, as well as a plethora of human cancers." (PMID 35203243, 2022). "Mutations in other putative RNA binding proteins, such as FUS, ataxin-2, SMN and FMRP, are associated with familial ALS, spinocerebellar ataxia, spinal muscular atrophy and fragile X syndrome, respectively." (PMID 20948999, 2010). "Remarkably, mutations in the ASC-1 complex are known to cause a severe form of Spinal Muscular Atrophy (SMA), and we show that an SMA-causative mutation in an ASC-1 component or an ALS-causative mutation in FUS disrupts association between the ASC-1 complex and the RNAP II/U1 snRNP machinery." (PMID 30398641, 2018).